IL33 (interleukin 33)
Diseases named in the same sentence as IL33 in open-access papers (continued):
Sharing a sentence is not in itself a finding about the gene and the disease.
tumor (continued). "In intratumoral Treg cells under a nutrient deficiency and sufficient immunosuppressive metabolites, intranuclear IL-33 can employ a cell-intrinsic role to shape the function and metabolic profile of Treg cells to promote tumor development." (PMID 35979357, 2022). "It has been reported that in Lewis lung cancer, IL-33 can increase the secretion of the antimicrobial peptide LL-37 from macrophages, resulting in excessive inflammation that can facilitate the tumor growth." (PMID 35634336, 2022). "On the contrary, the inhibition of CD26 can improve antitumour immune response by enhancing the effect of eosinophils through IL‐33‐depended eosinophil‐mediated control of tumour growth." (PMID 35344301, 2022). "Toluidine blue staining revealed increased accumulation of CTMC at the tumour margins and within the gastric submucosa in gp130F/F compared to gp130F/F/Il33−/− mice." (PMID 35677533, 2022). "The members of the IL-1 subfamily including IL-1β and IL-33 drive tumor promotion and immune suppression." (PMID 35572545, 2022). "Reduced tumour burden in gp130F/F/Il33−/− mice was correlated with decreased gastric epithelial proliferation, inflammation and protumorigenic cytokine/chemokine expression associated with alternative M2 macrophage activation." (PMID 35677533, 2022). "For instance, IL-33 activated hILC2s, which released granulocyte-–macrophage colony-stimulating factor (GM-CSF) and eosinophils were attracted to the tumor location." (PMID 36246629, 2022). "It was also shown that IL33-stimulated tumour-associated macrophages (TAMs) were the primary source of CXCL3, and that CXCL3 and IL33 were correlated with poor survival." (PMID 36358721, 2022). "Our RT-qPCR analysis of Il33 and RAB pathway mRNAs confirmed these observations as Il33 transcripts were significantly increased in all tumors and reduced in knockout samples in both tumor and normal tissues." (PMID 35091681, 2022). "For instance, lactic acid from tumor cells is pro-tumorigenic whereas higher levels of IL-33 in TME are shown to induce antitumorigenic activities of ILC2s." (PMID 35844571, 2022). "Conversely, Sox9 (a Wnt and Yap1-target gene) and some canonical targets of Yap/Tead such as Cyr61 and IL33 which have known roles in stem cell maintenance, cell migration and tumor invasiveness - were repressed by AHR." (PMID 35383166, 2022). "The IL-33/ST2 pathway promotes tumor progression by suppressing anti-tumor immunity and promoting angiogenesis." (PMID 36012144, 2022). "Inflammatory cells are also present in the TME, where they modulate tumor growth by the secretion of active molecules (such as IL-1β, IL-33, IL-6, TNF-α, and IL-17) into the TME." (PMID 36588722, 2022). "Serum IL-31 was related to tumour stages (p = 0.024), and serum IL-33 was related to tumour stages (p = 0.035), depth of invasion (p = 0.008), nodal metastases (p = 0.029) and distant metastases (p = 0.036)." (PMID 34951691, 2022). "In contrast, epidermal IL-33 contributes to a microenvironment that supports tumor growth and progression in murine skin." (PMID 35432341, 2022). "In mouse models, administration of IL-33 induces DC activation to enable cross-priming of tumor-reactive CD8+ T cells to inhibit tumor growth." (PMID 36291105, 2022). "We further found that tumor samples from Nfe2l3 knockout animals displayed significantly reduced IL33 expression when compared to wild type." (PMID 35091681, 2022). "Similar antitumor activity has also been described in lung ILC2s, as IL-33-activated ILC2s produce cytokines IL-5 and IL-13, recruiting eosinophils and DCs to the tumor site, respectively, which limits tumor growth and invasion." (PMID 35409105, 2022). "During this inflammatory response, increasing pleiotropic pro-cancer cytokines, such as IL-33, IL-6 are secreted and act pro-tumor cytokine to facilitate LC progression." (PMID 35068336, 2022).
tumor (continued). "Studies have shown that the inhibition of the IL-33/ST2 pathway enhances anti-tumor immunity and slows down the progression of tumors." (PMID 36012144, 2022). "In a CT26 subcutaneous model of CRC, exogenous IL-33 increased tumour size and correlated with ST2+ Treg tumour infiltration." (PMID 36263033, 2022). "We too observed IL-33 dependent enrichment of toluidine blue-stained CTMCs specifically at tumour margins in gp130F/F mice." (PMID 35677533, 2022). "In mouse genetic studies, we show that genetic ablation of IL-33 restrains tumour growth as well as limiting the recruitment of tumour promoting mast cells and immunosuppressive M2 macrophages, which are key drivers of gastric tumorigenesis." (PMID 35677533, 2022). "Histological analysis of antral stomachs revealed a higher concentration of inflammatory infiltrate in the mucosal/submucosal space at the base of gp130F/F tumours compared with the gp130F/F/Il33−/− antrum." (PMID 35677533, 2022). "More pCR was seen in patients where pretreatment biopsies showed CD8 = CD3, CD8 ≥ CD4, positive IL33 tumor cell scores, and IL33 in immune cells < tumor cells." (PMID 35566403, 2022). "In PDAC, ILC2s recruit DCs to promote antitumor immunity, but decreasing ILC2s by genetic deletion of IL-33 improves the survival of tumor-bearing mice." (PMID 35720302, 2022). "In a colon cancer model, IL-33 can increase interferon (IFN)-γ production by tumor-invasive CD4+ and CD8+ T cells." (PMID 35464435, 2022). "IL-33 inhibits tumor growth and lung metastasis in many mouse models by recruiting and activating eosinophils." (PMID 36291105, 2022). "Conversely, activation of CLEC7A can exert effective anti-tumor immunity by enhancing the expression of interleukin-33 and interleukin-9 in dendritic cells and by inducing differentiation of naive CD4+T cells into T-helper 9 cells." (PMID 35480896, 2022). "IL-33 is a tumor suppressor, but its upregulation in lung epithelial cells is contributed to the hyperinflammation in patients with severe SARS-CoV-2." (PMID 35432340, 2022). "IL‐33 can have opposite functions in cancer field, promoting or dampening tumour immunity, depending on the tumour type, site of expression and local concentration." (PMID 35344301, 2022). "Eosinophil-mediated anti-tumoral function, driven through the recruitment of eosinophils by IL-33 into the tumor site, has also been reported." (PMID 35159247, 2022). "For example, IL-33 has been shown to have potent anti-tumor activity against CRC cells that is dependent on the presence of eosinophils, which are recruited, activated, and degranulated by IL-33." (PMID 35205776, 2022). "On one hand, binding of IL-33 to ST2L can promote the tumor cell growth, proliferation and metastasis by inducing Th2-type cytokines and promoting the accumulation of immunosuppressive cells in tumors." (PMID 35634336, 2022). "Galectin-1 and IL-33 share the same tumor promoting effect in CRC, by helping tumor cells in bypassing of apoptosis." (PMID 35611243, 2022). "IL-33 exerted a positive effect on FoxP3 induction, thus increasing the frequency of Tregs in the tumor-infiltrating lymphocytes, which was partially dependent on M2 TAMs." (PMID 35634336, 2022). "NSCLC cells secrete IL-33 to increase the frequency of Tregs in tumor-infiltrating lymphocytes, which can lead to immune escape." (PMID 35634336, 2022). "Overexpression of IL-33, which has been suggested to correlate with tumor progression in humans, facilitates tumor growth and metastasis by upregulating GLUT1 and, consequently, enhancing glycolysis in NSCLC nude mice." (PMID 36532721, 2022). "Exogenous IL-33 treatment reduced tumour burden in the AOM/DSS model of CAC and correlated with increased eosinophil infiltration." (PMID 36263033, 2022). "In our studies we have shown that IL-33 is increased in HCC tumors as well and high ILC2 concentration in the tumor was associated with better survival." (PMID 35663967, 2022).
tumor (continued). "Endogenous IL-33/ST2 signaling enhances tumor-infiltrating ILC2s and CD8+ T cell-mediated cancer immunity in pancreatic ductal adenocarcinoma-bearing mouse models." (PMID 36291105, 2022). "We found that FOXP3 is a good prognostic factor for patients with high IL-33 and TGFb2 in the tumor." (PMID 35565267, 2022). "In CRC, IL-33 is predominantly expressed by tumour epithelial cells and is upregulated in both human and mouse (Apcmin/+) intestinal tumours compared to the adjacent normal gut." (PMID 36263033, 2022). "A portion of IL33 that is produced by lymphocytes enables c-kit + Sca + IL-7Ra, which are responsible for tumor immune surveillance and tumor tissue entry and proliferation." (PMID 36567723, 2022). "It is reported that the expression of IL-33 in the tumor tissue samples of NSCLC patients significantly decreased compared with that in adjacent tissue." (PMID 35634336, 2022). "We showed that loss of NFE2L3 leads to less inflammation and a change in the tumor microenvironment, with a reduced number of mast cells and an increase in regulatory T cells, mediated through signaling via the IL33 and RAB pathways." (PMID 35091681, 2022). "In contrast, IL-33 decreases the accumulation of MDSCs with reduced immunosuppressive ability in the spleen and tumor in a B16 melanoma-bearing mouse model." (PMID 36291105, 2022). "Our RT-qPCR analysis revealed that in normal non-tumor tissue, Il33 transcripts were expressed at significantly lower levels in Nfe2l3−/− specimens whereas the RAB pathway genes were unaltered." (PMID 35091681, 2022). "In conclusion, IL-33 can inhibit lung tumor metastasis and tumor cell proliferation by increasing the proliferation and activation of immune cells and promoting their infiltration into various tissues." (PMID 35634336, 2022). "Collectively these data identify IL-33 as a likely cell autonomous cytokine driver of tumour growth in GC." (PMID 35677533, 2022). "IL‐33 represents a promising immune adjuvant for vaccine therapy, tumour biomarker and therapeutic target." (PMID 35344301, 2022). "The summarized results in this review suggest that IL-33 exerts dual-functioning, pro- as well as anti-tumorigenic effects depending on the tumor type, expression levels, cellular context, and cytokine milieu." (PMID 34209038, 2021). "Numerous studies demonstrate IL-33 plays a key role in regulating neoplastic transformation, tumor growth, and metastasis in many cancers." (PMID 34209038, 2021). "Since tumor FSCs exhibited increased IL-33 production after artLCMV-TRP2 injection, we considered it likely that CD8+ T cells respond locally to this cytokine." (PMID 34354077, 2021). "Interleukin-33 (IL-33), a tissue-derived nuclear cytokine from the IL-1 family, has been found abnormally expressed in tumor cells and Fibroblast." (PMID 34895039, 2021). "Additional rescue experiments suggested that overexpressing NORAD or IL-33 markedly reversed the anti-tumor role of miR-496 in GC." (PMID 34895039, 2021). "Because Eomes is a master transcription factor and has been implicated in regulating differentiation of many CD8+ T cell subsets, we set out to investigate the effect of Eomes on the IL33-based tumor immunotherapy." (PMID 33553191, 2021). "Recruitment of eosinophils via IL-25 and IL-33 by innate IL-5-producing cells was shown to be critical in suppressing tumor cell dissemination to the lung." (PMID 34884995, 2021). "We subcutaneously injected IL‐33 in the areas surrounding tumour mass every alternate day using PBS as the control." (PMID 33305406, 2021). "Yang and colleagues have illustrated the interaction mechanism between perivascular cells and TAMs and their ability to promote metastasis through an IL-33/ST2-dependent pathway in a tumor-xenograft mouse model." (PMID 33628592, 2021). "IL‐33, a pro‐inflammatory cytokine from the IL‐1 family, regulates the host immune response and promotes tumour growth." (PMID 33305406, 2021).
tumor (continued). "To conclude, perivascular cells induce TAMs M2 and pro-angiogenic phenotype via MFG-E8 and IL-33 secretion, which impacts tumor growth." (PMID 33783686, 2021). "In order to understand the molecular underpinning of IL33-driven antitumor immunity, we examined Eomes expression in B16-IL33 tumor tissues." (PMID 33553191, 2021). "We compared the abundance of 34 types of immune cells in the tumor samples between the high and low IL-33 groups." (PMID 33621202, 2021). "It has been found that IL-33, because of its strong correlation with increased GAMs, plays a proinflammatory role in the tumor microenvironment and thus promotes tumorigenesis in HGGs." (PMID 33561993, 2021). "IL11, possibly secreted from subepithelial myofibroblasts or tumor-associated endothelial cells, signals through STAT3 and stimulates gastric tumor epithelium to release IL33." (PMID 34235145, 2021). "A number of studies with various tumor models reported that IL-33 is capable of expanding MDSCs during cancer progression." (PMID 34209038, 2021). "In line with this, recent research has described a central role for IL‐33 in tumor immunity, metabolic disease, inflammation, and infection." (PMID 33222176, 2021). "In the TME, the potential sources of IL-33 are epithelial cells, keratinocytes, endothelial cells, pericytes, fibroblasts, smooth muscle cells, and tumor cells (namely, melanocytes)." (PMID 33621202, 2021). "To validate our vitro findings, we chose a zebrafish tumor model for assessing the immunosuppressive effect of IL‐33‐stimulated macrophages." (PMID 34486239, 2021). "At this stage, further investigation into the downstream signaling pathway activated in tumor cell lines is warranted in order to understand the exact mechanism by which IL-33 promotes apoptosis and inhibits proliferation." (PMID 34071419, 2021). "Taken together, these findings suggest the divergent effects of IL-33/ST2/ILC2 on tumor immunity in different tissues through multiple distinct mechanisms." (PMID 34209038, 2021). "These IL-33 recruited TAMs are also involved in tumor growth and in cancer cell stemness via prostaglandin 2 secretion." (PMID 33783686, 2021). "PD-L1 and IL-33 were assessed separately in tumor cells (TCs) and tumor-infiltrating lymphocytes (TILs)." (PMID 34572318, 2021). "It has been shown that IL-33 promotes tumor invasion by regulating chemokine CCL2 and by recruiting Tregs." (PMID 33390169, 2021). "The tumour xenograft assay in nude mice was used to examine the role of IL‐33 in ESCC development in vivo." (PMID 33305406, 2021). "The IL1RL1/IL-33 axis can remodel the tumor stroma or microenvironment to promote malignancy by recruiting a cohort of immune cells." (PMID 34610582, 2021). "Ornithine secreted by M2 macrophages promotes tumor growth and metastasis by activating tumor cell IL-33 expression." (PMID 34445193, 2021). "An additional study showed that IL-33 dependent tumor-infiltrating ILC2s were able to mediate tumor immune surveillance by cooperating with DC to promote cytolytic CD8+ T cell responses." (PMID 34209038, 2021). "In tumor microenvironment, it has been found that IL-33 induces macrophages to infiltrate into tumor tissues to produce prostaglandin E2 which makes tumor cells to acquire CSCs’ stemness and to support proliferation of CSCs in CRC." (PMID 33898430, 2021). "IL-33 is a relatively new member of the IL-1 family and it is expressed by non-hematopoietic cells such as endothelial cells within human tumor tissues of kidney, stomach, liver, pancreas, lung, breast, or colon cancers." (PMID 34063627, 2021). "We performed WB to determine IL‐33 levels to verify the previous results and found considerably elevated secretion of IL‐33 in tumour tissues compared with the non‐tumour tissues." (PMID 33305406, 2021). "In our study on a murine AML model, we showed that systemic administration of IL-33 induced DC activation and “licensing” for cross-priming of tumor-reactive CD8+ T cells." (PMID 34209038, 2021).
tumor (continued). "Stimulation with IL-33 preferentially skews the cell differentiation towards the Th2 phenotype, which is traditionally considered to favor tumor growth." (PMID 34209038, 2021). "IL‐33 upregulated the cytotoxicity of NK cells and inhibited tumor cells growth in the effective cetuximab treatment mice." (PMID 34664425, 2021). "A previous study showed that IL-33 is enriched in CAFs and released into the tumor microenvironment." (PMID 34895039, 2021). "Pretreatment of STILs with conditioned media from the SB‐3CT‐treated IL‐33‐MMCs and IL‐33‐HMCs also rescued the tumor killing effects." (PMID 34486239, 2021). "In mouse models of metastatic melanoma, an anti-tumor activity of ILC2s activated by IL-33 has been shown; in this case, ILC2 cells release IL-5, which in turn recruits eosinophils exerting an anti-tumor activity, as also described in CRC." (PMID 34680190, 2021). "The crosstalk between tumor cells and surrounding stroma is proved by the occurrence that IL-33 upregulation in tumor correlates with increased expression of target receptor complex IL-1 receptor-like 1 in stromal cells, indicating a paracrine effect of IL-33." (PMID 33806300, 2021). "Endogenous IL-33/ST2 signaling triggers either pro- or anti-tumor immune responses across different cell types in both autocrine and paracrine manners." (PMID 34209038, 2021). "Effective cetuximab treatment induced an increase of IL‐33 at the early stage and promoted the cytotoxic activity of NK cells to counter against tumor cells." (PMID 34664425, 2021). "Based on the results of cell killing and cell proliferation, we noted that the survival rate of HT‐29 tumor cells following treatment with IL‐33 and cetuximab was significantly lower compared with those treated only with cetuximab." (PMID 34664425, 2021). "Sustained IL-33 production local to tumours was found to induce massive proliferation of intratumoral ILC2s, which stopped tumour growth." (PMID 34638291, 2021). "Here we summarize the pleiotropic characteristics of IL-33 and recent advances in preclinical research with a focus on its dual role in regulating tumor immune escape, revealing its potential as a target for cancer immunotherapy." (PMID 34209038, 2021). "We recently showed that IL33 was induced by PD-1 monoclonal antibodies (mAbs) in tumor cells and was crucial for the antitumor effect of this checkpoint inhibitor in mouse tumor models." (PMID 33553191, 2021). "During cancer initiation and progression, the aberrant regulation of the IL-33/ST2 axis in the tumor microenvironment (TME) extrinsically and intrinsically mediates immune editing via modulation of both innate and adaptive immune cell components." (PMID 34209038, 2021). "Our data clearly demonstrated that Eomes deficiency greatly enhanced antitumor activities and increased the durability of IL33 and checkpoint blockade tumor therapy models." (PMID 33553191, 2021). "Accumulating evidence demonstrates both pro- and anti-tumorigenic properties of IL-33, depending on the complex nature of different tumor immune microenvironments." (PMID 34209038, 2021). "Here, we found that in patients with ESCC, the tumour tissue samples had elevated levels of IL‐33 compared with non‐tumour tissue samples." (PMID 33305406, 2021). "Whereas some reports suggest that immunoreactive serum IL-33 is a biomarker for a favorable tumor prognosis, other studies outline its pro-tumorigenic role, particularly its effects on anti-tumor immunity." (PMID 34504486, 2021). "Since ILC2s have been found to express PD-1, the combination of anti-PD-1 blocking antibodies together with IL-33 improved anti-tumor responses through the expansion of tumor-infiltrating ILC2s accompanied by eosinophils." (PMID 34691082, 2021). "IL-33 expression is notable because it promotes tumor growth and metastasis of tumor cells, and it can promote antitumor immunity via its effect on helper T cells." (PMID 34433873, 2021).